TMBIM6 (transmembrane BAX inhibitor motif containing 6)
Diseases named in the same sentence as TMBIM6 in open-access papers (continued):
Sharing a sentence is not in itself a finding about the gene and the disease.
cancer (continued). "High expression of TMBIM6 has been observed in many cancer types, such as breast, prostate, non-small cell lung, nasopharyngeal, and pulmonary adenocarcinoma." (PMID 31336725, 2019). "Transmembrane Bax Inhibitor Motif-containing 6 (TMBIM6) is upregulated in several cancer types and involved in the metastasis." (PMID 31336725, 2019). "Furthermore, our findings suggest that TCF3-mediated regulation of TMBIM6 modulates Ca2+-dependent ferroptosis, thereby promoting cancer progression." (PMID 40610429, 2025). "TMBIM6, a Ca2+ channel-like protein, shows an increased expression in numerous types of cancer." (PMID 40610429, 2025). "Research has highlighted the significance of TMBIM6 in cancer biology." (PMID 38766879, 2024). "In addition, we identify that the BIA compound, a potentialTMBIM6 antagonist, prevents TMBIM6 binding to mTORC2, decreases mTORC2 activity, and also regulates TMBIM6-leaky Ca2+, further suppressing tumor formation and progression in cancer xenograft models." (PMID 32782388, 2020). "TMBIM6 disruption restricted primary tumor growth and impaired cancer cell metabolism." (PMID 32782388, 2020). "Understanding the basal and enhanced transcriptional regulation of the human TMBIM6 gene could be useful in identifying innovative strategies for specific cancer therapies and regulating TMBIM6 expression to protect against cellular injury." (PMID 31336725, 2019). "Additionally, TMBIM6 overexpression promotes cancer metastasis by regulating the actin polymerization, glucose metabolism, and mitochondrial function." (PMID 31336725, 2019). "Increased expression of TMBIM6 in some cancers is not due to any mutations in the upstream or coding region, rather it resulted from transcriptional regulatory elements in the tumor environment." (PMID 31336725, 2019). "Additionally, we also worked to identify the possible mechanisms involved in the enhanced TMBIM6 gene expression found in cancers by analyzing various chemical inducers." (PMID 31336725, 2019). "Specific downregulation of TMBIM6 results in cancer cell death." (PMID 31336725, 2019). "In this study, we found that Sp1-dependent TMBIM6 overexpressing cells are less sensitive against paclitaxel and cyclophosphamide treatment, indicating a role of Sp1-dependent TMBIM6 expression in the cancer cells resistance to stress." (PMID 31336725, 2019). "Furthermore, this study explored the significance of the Sp1 and PKC in the upregulation of TMBIM6 expression in cancers." (PMID 31336725, 2019). "A high level of TMBIM6 expression mediates resistance to apoptosis in carcinoma cells." (PMID 31336725, 2019). "Only two cancer associated genes PFDN5 and TMBIM6 were found in the deleted region." (PMID 24098698, 2013). "However, the TMBIM6 gene transcriptional regulation in normal and cancer cells is least studied." (PMID 31336725, 2019). "Our findings extend this body of work by focusing on TMBIM6, a gene previously less studied in PRAD but known to regulate cell death and stress responses in other cancers." (PMID 41516091, 2025). "Since the loss of epithelial morphology and the acquisition of mesenchymal characteristics are typical for carcinoma cells during tumor progression 56, 57, we also examined the expression of common EMT markers in TMBIM6-overexpressing cells." (PMID 37057283, 2023). "Specifically, the characteristics of BIA indicate the dissociation between RICTOR and TMBIM6 through the regulation of TMBIM6-leaky Ca2+ and the resultant inhibition of AKT activation impeding cancer formation." (PMID 32782388, 2020). "Thus, TMBIM6 may be an important regulator of cancer-related signaling." (PMID 32782388, 2020). "We identified BIA as an inhibitor of the interaction between TMBIM6 and mTORC2, which ultimately blocks AKT activation and cancer progression." (PMID 32782388, 2020). "To date, there is no report that has revealed the interaction between TMBIM6 and miR-181a in human cancers." (PMID 37057283, 2023).
cancer (continued). "Interestingly, TMBIM1, TMBIM2, TMBIM4, and TMBIM5 were found to decrease in many types of cancer, but TMBIM3 and TMBIM6 were significantly increased in this analysis." (PMID 37057283, 2023). "Without regard to synteny, the gene aligns with the gene TMBIM6, which is overexpressed in certain cancer types and suppresses Bax-induced apoptosis." (PMID 31728160, 2019). "Later, different carcinoma cell lines such as MDA-MB 231, MCF7, DU145, and HT1080 were transfected with P9-TMBIM6-HA or P9-(mSp1d, mSp1p)-TMBIM6-HA and treated with anticancer agents paclitaxel and cyclophosphamide at different concentration for 24 h, then cell viability was assessed." (PMID 31336725, 2019). "However, despite evidence of TMBIM6 overexpression in cancer cells, the molecular mechanisms by which TMBIM6 regulates cancer cell phenotypes are not clear." (PMID 37057283, 2023). "At least in resting condition, TMBIM6 is not a simple ER stress regulator but rather a core protein enhancing mTORC2 recruitment and assembly, ultimately affecting AKT activation and cell proliferation, especially in cancer." (PMID 32782388, 2020).
tumor (21 papers, 2010 to 2025). "Immune infiltration analysis suggested that up-regulated TMBIM6 expression is associated with higher epithelial cell enrichment in the tumor microenvironment." (PMID 41516091, 2025). "ov-TCF3 led to a notable rise in tumor volume, weight, and levels of TMBIM6 and GPX4, while causing a significant decrease in tumor Ca2+ concentration." (PMID 40610429, 2025). "Here, the authors show that TMBIM6 regulates AKT activation through mTORC2 assembly and ribosome association and identify an antagonist of TMBIM6 with anti-tumor properties." (PMID 32782388, 2020). "TMBIM6, also commonly known as BAX-inhibitor 1 (BI-1), has been related to the activation of mechanistic target of rapamycin complex 2 (mTORC2) and AKT, implicated in tumor development." (PMID 41516091, 2025). "Co-expression analysis was used to identify pathways involved in tumor progression, and immune infiltration analysis suggested that there is a correlation between the expression of TMBIM6 and the abundance of epithelial cells." (PMID 41516091, 2025). "In vivo, ov-TCF3 promoted tumor volume, weight, and TMBIM6 expression, and inhibited Ca2+ concentration, while Erastin reversed these changes." (PMID 40610429, 2025). "Nude mice xenografts injected with the TU-212 cells revealed that knockdown of TMBIM6 counteracted the effects of increased RBM15 on tumor volumes." (PMID 33637103, 2021). "Consistently, nude mice xenografts injected with the AMC-HN-8 cells revealed that knockdown of RBM15 counteracted the effects of increased TMBIM6 on tumor volumes." (PMID 33637103, 2021). "Tumor formation and the weight of tumors originating from TMBIM6 KO HT1080 cells was significantly reduced compared with that in WT cells." (PMID 32782388, 2020). "Consistently, tumor formation and weight, and the expressions of Ki-67 was apparently reduced in TMBIM6 KO HeLa cells than WT cells." (PMID 32782388, 2020). "BIA has emerged as a potential candidate as an antagonist regulating TMBIM6-mTORC2 interaction and its related tumor growth even in cases that are resistant to mTOR inhibitors." (PMID 32782388, 2020). "This study indicates that TMBIM6 is an important regulator of mTORC2 activity and tumor cell bioenergetics." (PMID 32782388, 2020). "To investigate the role of TMBIM6 in the growth of tumor cells in animals, we subcutaneously injected TMBIM6 WT and KO HT1080 cells into the left and right flanks of immunocompromised mice." (PMID 32782388, 2020). "Taken together, these in vitro and in vivo experiments demonstrate that TMBIM6 regulates tumor growth." (PMID 32782388, 2020). "Together, these opposing transcriptional patterns are consistent with the emerging notion that elevated TMBIM6 expression contributes to an immunosuppressive tumor microenvironment in PRAD, promoting tumor cell fitness while dampening anti-tumor immune pressure." (PMID 41516091, 2025). "Such enrichment suggests that TMBIM6 upregulation may reinforce proteostasis and metabolic adaptation programs that are advantageous for tumor progression." (PMID 41516091, 2025). "TMBIM6 is involved in tumor progression and metastasis in NSCLC." (PMID 36639675, 2023). "However, the expression of tumor suppressor miRNAs (miR-133b, let-7a, miR-137, miR-497, and let-7d) was significantly increased in TMBIM6 knockdown cells." (PMID 37057283, 2023). "The knockdown or deletion of TMBIM6 prevents primary tumor growth." (PMID 37685980, 2023). "Suppression of TMBIM6 leads to cell death, which results in reduced tumor development." (PMID 32782388, 2020). "TMBIM6 deletion or knockdown suppresses primary tumor growth." (PMID 32782388, 2020). "The genes most positively associated with TMBIM6 expression, including LAMP2, APLP2, TMED10, PPAPDC2, ZNF652, and CTSB, are primarily involved in lysosomal and ER trafficking, membrane dynamics, and metabolic resilience—pathways that facilitate tumor survival under cellular stress conditions." (PMID 41516091, 2025).
tumor (continued). "TMBIM6, a transmembrane BAX inhibitor motif containing six proteins, is correlated with tumor progression and metastasis." (PMID 41516091, 2025). "Initially, differential expression analysis of TMBIM6 was performed using data from four GEO datasets (GSE17951, GSE20979, GSE179321, and GSE32571) and TCGA_GTEx, comparing tumor (T) and normal (N) tissue groups." (PMID 41516091, 2025). "Highly expressed IGF2BP3 can directly bind to the m6A-modified region of target mRNA, thereby promoting the stability and expression of specific genes, such as TMBIM6, VEGF, and ABCB1, leading to tumor progression, angiogenesis, and chemoresistance." (PMID 35136045, 2022). "The proteomic analyses revealed that the combination treatment significantly downregulated tumour-promoting genes such as HLA-F, TRIAP1, TMBIM6, and ENTPD8, suggesting reduced mitochondrial integrity and immune escape, thereby enhancing apoptotic susceptibility." (PMID 41516237, 2025). "Tumors with low TMBIM6 expression exhibit significantly higher immune and stromal scores, indicating increased infiltration of non-tumor cells within the tumor microenvironment." (PMID 41516091, 2025).
infection (16 papers, 2013 to 2025). The state of being infected such as from the introduction of a foreign agent such as serum, vaccine, antigenic substance or organism. "So, we infer that the decrease in the TMBIM6 expression leads to the disorder of Ca2+ concentration, which promotes the infection of SARS-CoV-2." (PMID 33744846, 2021). "As shown in, the top ten proteins coexpressed with the viral proteins in the blue module demonstrated that TMBIM6 showed prominent coexpression with all detectable viral proteins, indicating that TMBIM6 is a key element influenced by the infection of SARS-CoV-2 in the cells." (PMID 33744846, 2021). "Interestingly, we found that TMBIM6 showed prominent coexpression with all viral proteins identified in the blue module, indicating that TMBIM6 is a key element influenced by the infection of SARS-CoV-2 in the cells." (PMID 33744846, 2021). "JQ-1 administration induced an upregulation of MAFK, TMBIM6, and NRF-2 target proteins, with a more pronounced effect in the presence of infection." (PMID 37747932, 2023).
metabolic disorders (4 papers, 2010 to 2024). "Other hub RMITRGs, such as HES1, TMBIM6, TSPAN13, and VMP1, also showed significant associations with metabolic diseases, highlighting the diverse molecular pathways involved in T2D." (PMID 39926598, 2024). "Given the critical role of the TMBIM6-NDUFS4-VDAC1 interaction in mitochondrial homeostasis regulation, exploring potential therapeutics targeting this axis could offer promising treatments for metabolic disorder-related endothelial damage." (PMID 39494338, 2024).
adenocarcinoma (1 paper, 2019). A common cancer characterized by the presence of malignant glandular cells. "A previous study reported that increased Krüppel-like zinc finger transcription factor 10 (Klf10) suppressed TMBIM6 expression in an estrogen-dependent manner and induced cell death in adenocarcinoma cells." (PMID 31336725, 2019).
neurological disorders (1 paper, 2026). "Although TMBIM6 exhibits neuroprotective effects in neurological disorders, its role in PD-related DAergic neuron survival remains unknown." (PMID 41932887, 2026).
TMBIM6 also shares sentences with these, for which no sentence is quoted: virus infection (5 papers); acute kidney injury (2); cardiovascular diseases (2); diabetes (2); fibrosarcoma (2); glioblastoma (2); Insulin resistance (2); nasopharyngeal carcinoma (2); Parkinson disease (2); Stroke (2); Arthritis (1); Autoimmunity (1); Babesia infection (1); bacterial infection (1); brain disorder (1); brain tumors (1); Burkitt lymphoma (1); cervical cancer (1); chronic hepatitis (1); chronic viral hepatitis (1); Cirrhosis (1); cognitive diseases (1); colorectal carcinoma (1); diabetic cardiomyopathy (1); diabetic encephalopathy (1); endocervical adenocarcinoma (1); esophageal squamous cell carcinoma (1); Glucose intolerance (1); hepatocellular carcinoma (1); hypoxic ischemic encephalopathy (1).
A further 19 diseases each share a sentence with TMBIM6 in 1 paper.